CBX7 (chromobox 7)
Diseases named in the same sentence as CBX7 in open-access papers (continued):
Sharing a sentence is not in itself a finding about the gene and the disease.
glioma (continued). "To assess the effect of Cbx7 on glioma cell lines, we performed a transient transfection of Cbx7 in various glioma cell lines and assayed for certain parameters." (PMID 27291091, 2016). "This infers that this pathway is mostly inactivated by mechanisms resulting from molecular events other than the somatic mutations of the pathway genes, thereby intimating to the role of epigenetic modifiers like Cbx7, which are also circumvented in glioma." (PMID 27291091, 2016). "U373 cells stably overexpressing Cbx7 (U373/Cbx7) also exhibited drastic reduction in growth as evidenced by colony suppression and reduced proliferation of glioma cells as compared to the vector control (U373/VC)." (PMID 27291091, 2016). "To further understand the necessity for Cbx7 silencing by promoter methylation in glioma, we carried out transcriptome profiling of U373 cell line transfected with control vector (U373/VC) or Cbx7 cDNA (U373/Cbx7) by whole RNA sequencing." (PMID 27291091, 2016). "We also found that Cbx7 was downregulated in glioma cell lines compared to the control brain samples and the treatment with methylation inhibitor resulted in the re-expression of Cbx7 transcript in three different glioma cell lines." (PMID 27291091, 2016). "Exogenous overexpression of Cbx7 induced cell death, inhibited cell proliferation, colony formation and migration/invasion of the glioma cells." (PMID 27291091, 2016). "To further verify whether CBX7 is hypermethylated in glioma cell lines and tissues, we predicted the CpG islands in the CBX7 promoter region and designed corresponding primers." (PMID 39988672, 2025). "CBX7 mRNA levels were observed to be lowest in grade 4 gliomas (p < 0.01)." (PMID 39988672, 2025). "Besides, as a tumor suppressor, CBX7 is pivotal to regulate tumor invasion and migration via the Wnt/β-catenin pathway in glioma." (PMID 36246611, 2022). "The glioma cells with the overexpression of CBX7 could improve the survival of implanted mice in vivo." (PMID 36034290, 2022). "Previous studies have shown that chromobox homologue 7 (CBX7) is ubiquitously expressed in glioma, endometrium, and other diseases, which may play a role in anticarcinogenesis." (PMID 33748425, 2021). "The expression levels of CBX7 are reduced in some tumors, and it is correlated with the clinicopathological parameters of several tumors, including breast cancer, bladder cancer, colon cancer, and glioma." (PMID 33748425, 2021). "We subsequently investigated whether DKK1 is a negative regulator of Wnt signaling in glioma cells overexpressing CBX7." (PMID 28388562, 2017). "Finally, in vivo bioluminescence imaging and survival times of nude mice revealed that CBX7 behaved as a tumor suppressor in gliomas." (PMID 28460453, 2017). "Chromatin Immunoprecipitation (ChIP) assays were conducted to test whether the CBX7 could bind to the CCNE1 promoter in glioma cells." (PMID 28460453, 2017). "We found that CBX7 possessed prognostic value in glioma patients." (PMID 28460453, 2017). "In summary, these findings showed that CBX7 inhibits glioma cell proliferation in vivo." (PMID 28460453, 2017). "We then examined CBX7 expression in normal and glioma samples from Jiangsu Province Hospital." (PMID 28388562, 2017). "To address this issue, we tested the function of CBX7 in glioma in vitro and in vivo." (PMID 28460453, 2017). "Our study also found lower CBX7 expression in higher grade gliomas." (PMID 28388562, 2017). "In summary, our results validate the assumption that CBX7 is a tumor suppressor of gliomas." (PMID 28460453, 2017). "Thus, in consideration of inhibiting neoplastic development, the role of CBX7 in glioma needs to be further investigated." (PMID 28388562, 2017). "In conclusion, CBX7 expression is highest in normal tissues and lower expression is seen in glioma, which might contribute to increased malignancy." (PMID 28388562, 2017). "We also found that CBX7 expression possesses subtype preferences within gliomas." (PMID 28460453, 2017).
glioma (continued). "In our study, we showed that CBX7 acted as a glioma suppressor via G1/S arrest." (PMID 28460453, 2017). "Thus, the CBX7-induced suppression of CCNE1, which encodes cyclin E1, contributed to the attenuation of glioma progression." (PMID 28460453, 2017). "Here, we demonstrated that CBX7 functions as a tumor suppressor in glioma by inhibiting invasion." (PMID 28388562, 2017). "Moreover, the exogenous expression of CTGF in Cbx7 stable background ensued in the rescue of the migratory potential of glioma cells." (PMID 27291091, 2016). "Moreover, exogenous overexpression of CTGF also significantly increased the pSAPK/JNK levels in Cbx7 stable glioma cells." (PMID 27291091, 2016). "Thus, our study identifies Cbx7 as an inhibitor of glioma cell migration through its inhibitory effect on YAP/TAZ-CTGF-JNK signalling axis and underscores the importance of epigenetic inactivation of Cbx7 in gliomagenesis." (PMID 27291091, 2016). "We have concentrated our efforts on Cbx7 regulation and its functions in the context of glioma." (PMID 27291091, 2016). "In glioma, the in vitro and in vivo functional assays results indicate that overexpression of miR-18a induced by miR-18a mimics may promote cell proliferation and migration of liver cancer cells by acting on CBX7." (PMID 34659360, 2021). "Moreover, CBX7 is a potential and novel prognostic biomarker in glioma patients." (PMID 28460453, 2017). "Therefore, we speculate that CBX7 can decrease EMT-like processes in glioma through similar mechanisms." (PMID 28388562, 2017). "Further analysis of glioma datasets from the TCGA and CGGA datasets indicated that CBX7 mRNA levels were downregulated in both low-grade and high-grade gliomas." (PMID 39988672, 2025). "The overexpression of CBX7 and underexpression of CBX8 significantly inhibited the proliferation and invasion of glioma cells in vivo and in vitro." (PMID 36034290, 2022). "The result indicated that overexpressed CBX7 and downregulated CBX8 in glioma cells showed a decreased expression of MMP2 and MMP9 and displayed significantly lower invasion abilities in scratch wound-healing assay when compared to the control." (PMID 36034290, 2022). "Next, we explored the effect of CBX7 and CBX8 on the proliferation capacity in these two glioma cells." (PMID 36034290, 2022). "Our results suggested that CBX7 and CBX8 served as independent prognostic indicators that promoted the proliferation and invasion of glioma cells, providing a promising strategy for diagnosing and treating GBM." (PMID 36034290, 2022). "Next, based on the gene regulation technology using lentivirus transfection, we established two models of CBX7-upregulated expression and CBX8-downregulated expression in the U87 and U251 glioma cells, respectively." (PMID 36034290, 2022). "Next, three glioma cell lines, LN229, T98G and PGC, were selected to investigate phenotypic changes following CBX7 overexpression." (PMID 28388562, 2017). "Further, bisulphite sequencing confirmed the hypermethylation of Cbx7 promoter in GBM samples (20.71%), glioma derived cell lines (39.60%) as compared to control brain samples (5.75%)." (PMID 27291091, 2016). "We observed a significant downregulation of Cbx7 transcript levels in GBM and low grade gliomas compared to control brain samples in our cohort, GSE 228866 and TCGA data sets." (PMID 27291091, 2016). "Pyrosequencing revealed that the methylation rate of CBX7 was higher in glioma cells, and clinical sample tests also showed that the methylation rate of CBX7 was higher in cancer tissues compared to adjacent non-cancerous tissues." (PMID 39988672, 2025). "Finally, we confirmed the roles of CBX7 and CBX8 in the proliferation and invasion of glioma cells in vivo and in vitro experiments, which provided a promising strategy for GBM treatments." (PMID 36034290, 2022). "Furthermore, we explored and confirmed the roles of CBX7 and CBX8 in the proliferation and invasion of glioma cells in vivo and in vitro." (PMID 36034290, 2022).
glioma (continued). "Our data confirm that CBX7 inhibits EMT and invasion in glioma, which is manifested by influencing the expression of MMP2, MMP9, E-cadherin, N-cadherin and Vimentin in LN229, T98G cells and primary glioma cells (PGC)." (PMID 28388562, 2017). "Genome-wide methylation analysis that was carried out using Infinium HumanMethylation450K BeadChip array, revealed Cbx7 as one of the hypermethylated genes in GBM and lower grades of glioma compared to control brain samples in our cohort, GSE 228867 and TCGA data sets." (PMID 27291091, 2016). "However, in a cohort which includes low grade gliomas, significant survival benefits were observed for patients with low EZH2, PHF19, CBX8 and PHC2 expression, and high CBX7, CBX6, RYBP and EZH1 expression." (PMID 24260522, 2013). "Other PRC1 members (CBX7, PCGF6) were selectively expressed in lower grade gliomas." (PMID 20920292, 2010). "In addition, CBX7 was found to regulate negatively migration and invasion via upregulation of E-cadherin and downregulation of matrix metalloproteinase (MMP)-2, MMP-9, and vimentin in glioma." (PMID 31709304, 2019).
thyroid cancer (18 papers, 2010 to 2024). "It has been reported that the loss of CBX7 is associated with a highly malignant phenotype in thyroid cancer." (PMID 34659360, 2021). "Studies showed that loss of the CBX7 expression correlated with a highly malignant phenotype in thyroid cancer, or a more aggressive biological behavior in pancreatic cancer." (PMID 29190923, 2017). "It was observed that loss of CBX7 expression correlated with aggressive phenotypes in thyroid carcinoma and colorectal carcinoma." (PMID 28030829, 2017). "The expression of another target, CBX7, decreases with malignancy grade and neoplasia stage in thyroid cancer and is associated with a more aggressive phenotype in pancreatic cancer." (PMID 21799901, 2011). "It was found that Loss of CBX7 expression correlated with a more aggressive phenotype in thyroid carcinoma, pancreatic adenocarcinoma and colorectal carcinoma." (PMID 20723236, 2010). "Likewise, loss of the CBX7 expression is correlated with a highly malignant phenotype in thyroid cancer." (PMID 31709304, 2019). "Downregulation of CBX7 indicated more aggressive phenotypes and worse survival in pancreatic cancer and thyroid cancer." (PMID 36140750, 2022). "According to prior studies, CBX7 was downregulated in colon cancer, pancreatic cancer, thyroid cancer and BC." (PMID 36140750, 2022). "The loss or downregulation of CBX7 gene expression was associated with several cancer, including PACA, thyroid cancer (THCA), CRC, NSCLC, bladder carcinoma (BLCA), and HCC." (PMID 33344640, 2020). "Loss of CBX7 expression has been described in several malignant neoplasias, including human colon and thyroid carcinomas proposing CBX7 as a tumor suppressor gene with a key role in cancer progression." (PMID 28259135, 2017). "Then, by using an Affymetrix cDNA microarray, we analysed the gene expression profile of thyroid carcinoma cells in which the CBX7 expression was restored, and identified several genes up- and down-regulated." (PMID 24865347, 2014). "We have previously demonstrated that the CBX7 gene is drastically down-regulated in thyroid carcinomas and its expression progressively decreases with malignant grade and neoplastic stage." (PMID 24865347, 2014). "Similarly, CBX7 acts as a tumor suppressor in several cancers including thyroid cancer, colorectal cancer." (PMID 34395271, 2021). "The decrease of CBX7 in thyroid cancer may be due to the negative regulation of tumor protein HMGA1." (PMID 34659360, 2021). "Moreover, restoration of CBX7 expression inhibits cell growth via retention of the cell cycle in thyroid cancer cells." (PMID 31709304, 2019). "Moreover, CBX7 expression is positively correlated with the E-cadherin level in human thyroid carcinomas." (PMID 31709304, 2019). "Thus, CBX7 may have slight influences on N-Cadherin expression, which is in accordance with previous studies in thyroid cancer." (PMID 28388562, 2017). "Furthermore, a recent study demonstrates that the loss of CBX7 observed in thyroid carcinomas leads to a negative or positive regulation of key genes involved in tumorigenesis, as the AP1 complex members FOS and FOSb, and the chemokine SPP1, respectively." (PMID 25595895, 2015). "To investigate the mechanism by which the loss of CBX7 expression may contribute to the acquisition of a malignant phenotype, we analysed the gene expression profile of a thyroid carcinoma cell line (FRO) in which the expression of CBX7 was restored (FRO-CBX7)." (PMID 24865347, 2014). "In addition, qRT-PCR assay performed on a panel of human thyroid carcinomas of different histotypes showed a positive correlation between HMGA1b and SPP1 expression while a negative correlation was observed between CBX7 and the expression of HMGA1b and SPP1." (PMID 25595895, 2015).
bladder cancer (15 papers, 2018 to 2025). "CBX7 is significantly downregulated in urinary bladder cancer (UBC) and correlates with poor prognosis." (PMID 41153362, 2025). "We investigated the methylation changes between the high- and low-expression groups of CBX6 and CBX7 and discovered that the methylation of CBX6 and CBX7 was considerably elevated in the bladder cancer group." (PMID 37189494, 2023). "CBX6 and CBX7 play a critical role in bladder cancer formation, as shown by the results of enrichment analysis based on their coexpressed genes, which revealed that they were associated with urothelial carcinoma and carcinoma and transitional cells." (PMID 37189494, 2023). "The link between high CBX7 mRNA expression and prognosis in bladder cancer was consistent with earlier research." (PMID 37189494, 2023). "It has been shown that PDE4B in our prognostic model gene induces epithelial-mesenchymal transition in bladder cancer cells and is transcriptionally repressed by CBX7." (PMID 36579330, 2022). "By analyzing eight CBX family members in TCGA dataset, we found that chromobox 7 (CBX7) was the most strikingly downregulated CBX family member in urinary bladder cancer (UBC), as compared to normal tissues." (PMID 34035231, 2021). "Further, the downregulation of AKR1B10 deactivates ERK activation in bladder cancer via CBX7." (PMID 39001490, 2024). "For example, CBX6 and CBX7 were identified as prognostic biomarkers in bladder cancer." (PMID 37938151, 2023). "We hypothesize that CBX7 exerts a tumor immune response by suppressing the immunological infiltration of M0 macrophages and attracting a significant number of resting mast cells, resulting in a better prognosis for patients with bladder cancer." (PMID 37189494, 2023). "To further verify our hypothesis, we transfected bladder cancer T24 cell with designed si HDAC4, si NFATC1 and si CBX7." (PMID 34405021, 2021).
ovarian carcinoma (15 papers, 2015 to 2025). A malignant neoplasm originating from the surface ovarian epithelium. "Our group has previously reported that CBX7 functions as a tumor suppressor in ovarian cancer cells and its loss accelerated formation of carcinomatosis and drove tumor progression in an ovarian cancer mouse model." (PMID 38037081, 2023). "Particularly, we found that almost all CBXs members except CBX7 were significate associated with B cell infiltration in ovarian cancer." (PMID 35155439, 2022). "Nevertheless, our studies have shown that CBX7 is a major regulator of ovarian cancer progression and that it can be regulated by factors secreted from adipocytes." (PMID 38037081, 2023). "Using conditioned media from human omental explants, we found that adipose-derived exosomes mediate CBX7 downregulation and enhance migratory potential of human ovarian cancer cells." (PMID 38037081, 2023). "Intriguingly, the single-cell sequence of RCC, acute lymphoblastic leukemia, and ovarian cancer indicated that CBX7 was negatively correlated with angiogenesis, proliferation and invasion." (PMID 35342353, 2022). "Conversely, overexpression of CBX7 and its oncogenic effects have been reported in lymphoma, prostate, and ovarian cancers." (PMID 36292141, 2022). "Significant down-regulation of CBX1 and CBX7 was found in ovarian cancer (OV) tissues compared to normal tissues, while the expression levels of CBX3 were significantly up-regulated in OV tissues." (PMID 35155439, 2022). "In ovarian cancer, CBX7 inhibits tumor growth and metastasis by binding to E-box to inhibit the function of TWIST147." (PMID 34117289, 2021). "Accordingly, inhibition of CBX7 decreased cell viability of ovarian carcinoma cell lines by promoting expression of TRAIL." (PMID 30481161, 2018). "Moreover, CBX7 knockdown significantly reduced cell viability in two ovarian carcinoma cell lines compared to the control cells, likely by the upregulation of tumor necrosis factor-related apoptosis-inducing ligand (TRAIL)." (PMID 28259135, 2017). "However, high expression of CBX7 mRNA was not related to OS (HR = 0.91 (0.79 - 1.06), P = 0.22) for all ovarian cancer patients whereas was linked to a worse PFS (HR = 1.35 (1.19 - 1.53), P = 0.0000) for all patients with ovarian carcinoma." (PMID 32742466, 2020). "Nevertheless, the prognostic value of the other five CBXs family members for predicting OS and PFS in ovarian cancer patients was either irrelevant (CBX5 and CBX8) or inconsistent (CBX4, CBX6, and CBX7)." (PMID 35155439, 2022). "As we previously reported, specifically for ovarian cancer, the expression of CBX7 alone is not predictive of survival." (PMID 38037081, 2023). "For example, CBX7 has been recently demonstrated to be overexpressed in ovarian cancer and reduced overall survival rates compared with patients not expressing CBX7." (PMID 35464847, 2022). "However, the results showed that the prognostic significance of CBX4-8 mRNA expression for predicting OS and PFS in all patients with ovarian cancer was inconsistent (CBX4, CBX6 and CBX7) or irrelevant (CBX5 and CBX8)." (PMID 32742466, 2020). "Equally, CBX7-positive patients affected by ovarian carcinoma showed significantly shorter overall and progression-free survival rates than those of the CBX7-negative patients." (PMID 28259135, 2017). "Whether or not CBX7 has a role in the initiation of ovarian cancer, such as exertion of pro-tumorigenic functions in normal ovarian surface epithelial cells or normal fallopian tube epithelial cells remains to be characterized." (PMID 38037081, 2023). "However, when used as a biomarker in conjunction Twist1, the absence of CBX7 in Twist1-positive ovarian cancer cells confers worse outcomes." (PMID 38037081, 2023).